UBE2C (ubiquitin conjugating enzyme E2 C)
Diseases named in the same sentence as UBE2C in open-access papers (continued):
Sharing a sentence is not in itself a finding about the gene and the disease.
tumor (continued). "Increasing evidence suggests that UBE2C mediates tumor progression through the Wnt signaling pathway." (PMID 39479352, 2024). "In order to ascertain the disparities in biological functions between the high UBE2C+ tumour cell score group and the low UBE2C+ tumour cell score group, we conducted an enrichment analysis." (PMID 38894657, 2024). "Taking into consideration the potential interplay between tumour cells and surrounding cellular components, we conducted an analysis of the cellular communication involving C2 UBE2C+ tumour cells." (PMID 38894657, 2024). "For instance, Docetaxel, a frequently utilized chemotherapeutic agent in the clinical setting for the treatment of GC, exhibited heightened sensitivity in the group characterized by a high UBE2C+ tumour cell score." (PMID 38894657, 2024). "With regard to myeloid cells, the liver-resident macrophages and inflammatory monocyte/macrophages were markedly replaced by tumor-associated macrophages (TAMs), with TREM2+ and UBE2C+ TAMs enriched in PTs, while SPP1+ and WDR45B+ TAMs in MTs." (PMID 38414027, 2024). "We investigated the biological function of UBE2C in regulating BCa lymphangiogenesis in vitro, which is a crucial step in tumor LN metastasis." (PMID 38949026, 2024). "Subsequently, we explored the disparity in TMB between the high UBE2C+ tumour cell score group and the low UBE2C+ tumour cell score group." (PMID 38894657, 2024). "Then, qRT-PCR and Western blotting were used to detect the expression of UBE2C in xenograft tumor tissues, respectively." (PMID 39334908, 2024). "The findings demonstrated that C2 UBE2C+ tumour cells were primarily enriched in ‘cycle’, ‘transition’, ‘segregation’ and ‘mitotic’ biological processes in both trajectories." (PMID 38894657, 2024). "Pseudotime analysis also showed that C2 UBE2C+ tumour cells had higher cell stemness and were in the early stage of cell differentiation and were, therefore, more malignant." (PMID 38894657, 2024). "Consistent with the findings from CytoTRACE analysis, the C2 UBE2C+ tumour cells were significantly concentrated in the initial stage of tumour cell development." (PMID 38894657, 2024). "We have identified a highly proliferative cellular subgroup C2 UBE2C+ tumour cells in GC for the first time." (PMID 38894657, 2024). "Among these, in the circle plots with C2 UBE2C+ tumour cells as the target, the communication signals between pericytes, fibroblasts and C2 UBE2C+ tumour cells were stronger." (PMID 38894657, 2024). "Some researchers have reported that UBE2C shows close relationship to tumor occurrence, proliferation, and other behaviors." (PMID 37808164, 2023). "The following series of phenotypic experiments showed that overexpression of UBE2C significantly rescued the decrease of tumor activity, cloning formation, proliferation, invasion, and migration caused by ZIC2 knockdown." (PMID 37496990, 2023). "Compared with normal tissues, the expression level of PLK1 was slightly higher, while that of UBE2C was obviously higher than tumor samples." (PMID 37958642, 2023). "Previous studies have reported that UBE2C can promote tumor proliferation by activating AKT/mTOR signaling pathway." (PMID 37496990, 2023). "The study elucidates regulatory mechanisms of METTL3/SNHG1/miRNA-140-3p/UBE2C axis in tumor progression and immune response in NSCLC." (PMID 36810034, 2023). "The positive expression of UBE2C and ZEB1 were positively associated with tumor stages, local lymph node metastasis, and International Federation of Gynecology and Obstetrics (FIGO) stages." (PMID 37335710, 2023). "It was also demonstrated that RIZ1, a tumor suppressor gene, is markedly decreased and regulates UBE2C in a c-Myc-dependent manner in malignant meningioma." (PMID 37958776, 2023). "Previous studies have pointed out the link between chemosensitivity and UBE2C, where downregulation indicates better tumor cell chemosensitivity to chemotherapeutic agents." (PMID 37840753, 2023).
tumor (continued). "Intratumoral heterogeneity was also evident in this analysis as for example characteristic marker genes for aNSCs (Hes6), TACs (Ube2c) and NBs (Stmn2) are expressed to different extents in the different tumor cell populations." (PMID 37407554, 2023). "In short, a series of studies shown that UBE2C is highly expressed in tumors tissues and able to promote tumor progression." (PMID 37535572, 2023). "Increasing evidence has revealed the importance of UBE2C as a potential candidate proto-oncogene functioning in tumorigenesis, tumor progression, epithelial-mesenchymal transitions (EMT), autophagy and cisplatin-based chemotherapeutic resistance." (PMID 37803076, 2023). "H&E staining showed clearly that tumor suppression by Ube2c deletion was completely rescued by simultaneous Deptor deletion in double-null mice with tumor burdens, similar to KrasG12D WT mice." (PMID 36548081, 2023). "RNA sequencing of thirty human BM identified the upregulation of UBE2C, a gene that ensures the correct transition from metaphase to anaphase, across different primary tumor origins." (PMID 37215954, 2023). "UBE2C was found to be highly expressed in BM samples from diverse primary tumor origins when compared to normal tissues." (PMID 37215954, 2023). "This causal role of DEPTOR is fully demonstrated by an in vivo rescue experiment, in which suppression of tumor growth by Ube2c KO is fully abrogated by simultaneous Deptor KO." (PMID 36548081, 2023). "As we analyzed the pathway involved in tumor development affected by UBE2C using GSEA, UBE2C turned out to be mainly enriched in DNA replication, mismatch repair, and cell cycle pathways." (PMID 37840753, 2023). "Remarkably, a study discovered that KrasG12D mutation regulates the cell cycle by promoting the expression of UBE2C, which ultimately promotes tumor cell growth." (PMID 37535572, 2023). "The difference is statistically significant (P = 0.0241), indicating that reduced tumor burden upon Ube2c deletion indeed led to better animal survival." (PMID 36548081, 2023). "Validation studies confirmed UBE2C immunostaining in 20 of 25 HB tumor specimens versus 1 of 6 normal liver samples." (PMID 37377594, 2023). "Collectively, these results demonstrated that the tumor-suppression phenotype resulting from Ube2c deletion was mainly mediated via DEPTOR accumulation and subsequent inactivation of mTORC1/2 signaling in the KrasG12D lung tumorigenesis model." (PMID 36548081, 2023). "A comprehensive bioinformatics analysis indicated the effect of UBE2C in promoting tumor progression, but the carcinogenic effect of UBE2C in ACC still needs to be further investigated." (PMID 37535572, 2023). "Ubiquitin-conjugating enzyme E2C (UBE2C), its overexpression promotes tumor progression, is a key component of the ubiquitin conjugating proteasome complex." (PMID 37335710, 2023). "Our study found that the combined knockdown of UBE2C with PLK1 significantly inhibited tumor cellular proliferation and triggered more lethal apoptosis and cell cycle arrest, compared to those of the knockdown of either alone." (PMID 37958642, 2023). "IHC analysis results revealed that circ_000829 overexpression reduced Ki-67 positive cells in tumor tissues, and that overexpression of circ_000829 diminished the expression of SRSF1 and UBE2C (proliferation- and invasion-related marker) in the tumor tissues." (PMID 36062189, 2022). "Regarding THCA, expression analyses on independent and paired samples indicated the higher expression of UBE2C in the tumor group than in the normal group." (PMID 35332135, 2022). "In univariate analysis, clinical characteristics (gender, age, T, N, M and tumor stage), APOA2, COX6A2, HIST1H1E, UBE2C, ERO1B and eight gene comprehensive risk scores were prognostic risk factors for patients with the EC (P < 0.05)." (PMID 35568702, 2022).
tumor (continued). "The tumor volume and weight of oe-ALKBH5 + sh-NC-treated mice were increased but opposite results were noted in the presence of oe-ALKBH5 + sh-UBE2C, suggesting that the tumor-promoting effect of ALKBH5 can be partially reversed by the silencing of UBE2C." (PMID 36551544, 2022). "Various studies have shown that lysine acetyltransferase 2A (KAT2A), E2F transcription factor 1 (E2F1), and ubiquitin conjugating enzyme E2 C (UBE2C) genes regulated the proliferation and migration of tumor cells through regulating the cell cycle." (PMID 36292703, 2022). "Univariate analysis showed that UBE2C expression, T stage, N stage, M stage, clinical stage, and person neoplasm status were related to DFS of THCA patients." (PMID 35332135, 2022). "High UBE2C mRNA and protein expressions were correlated with features of poor prognosis, including high tumour grade, large size, the presence of lymphovascular invasion, hormone receptor negativity and HER2 positivity." (PMID 35124721, 2022). "Previous studies have reported that UBE2C expression levels were predictive of a higher rate of pathological complete response rate in luminal A patients with tumor relapse within five years of endocrine therapy." (PMID 36069832, 2022). "The expression of miR-205-5p (p < 0.0001) and UBE2C (p = 0.0093) were upregulated in tumor tissues, while the expressions of miR-140-3p (p = 0.0293), PTPRM (p < 0.0001), GPD1L (p = 0.0002), and FOXF2 (p < 0.0001) were downregulated in tumor tissues." (PMID 35712349, 2022). "Another study has shown that ubiquitin-conjugating enzyme E2C (UBE2C) is highly expressed in many tumors and inhibition of UBE2C inhibits tumor progression." (PMID 35543375, 2022). "The downregulation of UBE2C facilitated tumor inhibition and the anti-immune effect was confirmed by in vitro experiments." (PMID 36385010, 2022). "Intriguingly, we noticed the activity of the ubiquitin-mediated proteolysis pathway, as well as the expression of multiple ubiquitin-conjugating enzymes including UBE2S, UBE2E3 and UBE2C, were upregulated in tumor cells from solid samples." (PMID 36138435, 2022). "To verify the clinical significance of UBE2C, we collected a set of tumour tissues paired with normal tissue (GEO accession number: GSE111168)." (PMID 34815392, 2021). "Compared with Control group, UBE2C-knockdown group had significantly inhibited tumour growth and reduced tumour volumes and weights." (PMID 34815392, 2021). "In the CCK8 assay, tumour cell growth was significantly decreased in all the UBE2C-knockdown Y79 cells, whereas the control cells retained a higher cell viability." (PMID 34815392, 2021). "As expected, UBE2C presented high expression in tumours and was higher in younger patients (<3 years old)." (PMID 34815392, 2021). "The possible targeting relationship among lncRNA, miRNA, and UBE2C in ESCC tumor tissue was further clarified by calculating the combined SMD of the candidate miRNA and lncRNA expression values." (PMID 34488675, 2021). "After performing correlation analysis, expression analysis, survival analysis, and luciferase activity assays, we can confirm that miR-140-3p was the most likely upstream tumor suppressor miRNA of UBE2C." (PMID 34858987, 2021). "After multiplying scores of intensity and percentage in positive cells of each tissues section, we found that the expression level of UBE2C was higher in tumor tissues than it was in CTAN tissues in all subsites of OSCC (p < 0.001)." (PMID 32899896, 2020). "Forced expression of miR-381 in HR-8348 cells dramatically inhibited UBE2C expression and tumor growth." (PMID 32984321, 2020). "The expression levels of UBE2C protein were higher in tumor tissues than they were in the corresponding tumor adjacent normal tissues from OSCC patients." (PMID 32899896, 2020).
tumor (continued). "Consistent with our findings, a previous study also demonstrated that up-regulation of UBE2C mRNA expression was frequently observed in HCC tissues and associated with tumor invasion, de-differentiation, and poor prognosis." (PMID 30914455, 2019). "UBE2C expression, based on patients’ pathological stages, showed that UBE2C overexpression can be involved in tumor progression and invasion." (PMID 31067633, 2019). "Among the UBE2C protein partners, TSPYL2 (a member of the testis-specific protein Y-encoded) is a tumor suppressor protein which acts in the chromatin remodeling process." (PMID 31067633, 2019). "We next assessed the expression levels of UBE2C with respect to the molecular and histological subtypes of tumors, tumor grades, and other patient conditions when data are available using UALCAN." (PMID 31067633, 2019). "The downregulation of UBE2C expression upon ICT treatment also confirmed the previous finding that UBE2C is important in the tumor cell growth in PCa cells." (PMID 31646760, 2019). "Data extracted from TCGA database revealed that UBE2C expression was notably higher in all 27 tumor types compared to matched TCGA normal tissues and GTEx data." (PMID 31067633, 2019). "Our results show that FOXM1 and UBE2C expression present a positive correlation in normal tissues and in 25 distinct tumor types, including ESCC, where these genes are overexpressed." (PMID 29596365, 2018). "In this study, we demonstrate that UBE2C is a transcriptional target of FOXM1 in ESCC, and likely present in several human neoplasias, thus further contributing to the loss of G2/M checkpoint control as a consequence of FOXM1 deregulation." (PMID 29596365, 2018). "In NSCLC, overexpression of UBE2C in tumor tissues was correlated with advanced tumor stage and apoptosis dependent cell proliferation." (PMID 29137415, 2017). "Abundant experimental evidence has shown a role for Ube2c in human tumor initiation and progression." (PMID 28049433, 2017). "According to the results reported here, UBE2C expression pattern has been already proposed as a promising molecular tool for the diagnosis of several tumor types." (PMID 27588470, 2016). "Recently, ubiquitin-conjugating enzyme E2C (UBE2C) has been figuring as a prominent tumor biomarker candidate, once it has been recognized as a key player in cell cycle progression." (PMID 27588470, 2016). "UBE2C expression was particularly present in tumor foci, especially in the tumor invasive front where the intensity of UBE2C immunostaining was very high." (PMID 27588470, 2016). "Our results are in accordance with the data already present in the literature, since UBE2C overexpression has been reported in several distinct tumor types." (PMID 27588470, 2016). "The analysis of UBE2C gene expression in 52 paired ESCC samples (tumor and respective histologically normal surrounding tissue), by qRT-PCR, revealed that this gene is overexpressed in 73% of ESCC samples." (PMID 27588470, 2016). "UBE2C is a E2 ubiquitin-conjugating enzyme that promotes tumor cell growth and malignant transformation." (PMID 27528424, 2016). "It is possible that higher tumor stage and overexpression of UBE2C and MGP in group A have contributed to the observed trend of worse outcome, because both factors have been associated with poor survival in ESCC." (PMID 27556859, 2016). "Analysis of E2F2, CDK1, CDC20, UBE2C and the proliferation biomarker Ki67 in xenograft sections showed consistently lower levels in the shASCT2 tumours." (PMID 25693838, 2015). "The expression of AR targeted genes including PSA, TMPRSS2 and UBE2C as well as the tumor proliferation index Ki67 were more strongly inhibited by ENZ plus ICRF187." (PMID 26009876, 2015). "High tumor grade, as well as increased Ki67 protein expression, was more frequent in tumors with a high level of expression of UBE2C [45−47]." (PMID 24489730, 2014).
tumor (continued). "Relative expression levels of the eight genes of interest (AZGP1, BIRC5, DHCR7, IL6ST, MGP, RBBP8, STC2, and UBE2C) were compared between paired whole tissue sections and tumor-enriched specimens." (PMID 25218890, 2014). "This suggests that UBE2C may promote tumor progression by inhibiting anti-tumor immune responses and enhancing stromal cell activity." (PMID 40290433, 2025). "Overexpression of UBE2C could suppress the anti-tumor immune response, impairing immune cells’ ability to recognize and eliminate tumor cells, thus allowing tumor cells to evade immune surveillance." (PMID 40290433, 2025). "Further investigations reveal that Halorotetin B binding to UBE2C induced M phase cell cycle arrest by inhibiting the ubiquitin-mediated degradation of key cell cycle regulators, including cyclin B1 and securin, ultimately leading to tumor cell senescence." (PMID 41387196, 2025). "The variation in UBE2C expression across different tumor types indicates that UBE2C exhibits diverse regulatory mechanisms in distinct types of tumors and is regarded as an oncogene that could be targeted for therapeutic purposes." (PMID 38577722, 2024). "UBE2C knockdown also suppressed the tumor formation of AML cells in the mouse model." (PMID 38637730, 2024). "Simultaneously, C2 UBE2C+ tumour cells influence the cells' oxidative phosphorylation pathway." (PMID 38894657, 2024). "Based on the outcomes derived from the GO_BP enrichment analysis, it became apparent that C2 UBE2C+ tumour cells were predominantly enriched in pathways such as ‘Cytoplasmic translation’, ‘Ribonucleoprotein complex biogenesis’, ‘Mitotic nuclear division’ and ‘Chromosome segregation’." (PMID 38894657, 2024). "Notably, the low UBE2C+ tumour cell score group exhibited a significantly elevated TMB compared to the high UBE2C+ tumour cell score group, with a statistically significant distinction (p < 0.01) between the two cohorts." (PMID 38894657, 2024). "Furthermore, the tumour purity in the low UBE2C+ tumour cell score group was higher than that in the high UBE2C+ tumour cell score group." (PMID 38894657, 2024). "Consequently, the comprehensive analysis of UBE2C+ tumour cells furnish a novel molecular biological standpoint concerning the unbridled proliferation of neoplastic cells." (PMID 38894657, 2024). "Aberrant protein expression of UBE2C was detected in 20 types of tumor tissues." (PMID 38577722, 2024). "UBE2C, through its function in promoting cell cycle progression, may exacerbate chromosomal instability, thereby contributing to tumor occurrence and progression." (PMID 39334908, 2024). "Additionally, we found that higher tumor grades in LUAD patients correlated with higher UBE2C expression (p<0.001)." (PMID 38370368, 2024). "Notably, UBE2C, belonging to the ubiquitin-conjugating enzyme (E2) family, is crucial for cell cycle progression and tumor development." (PMID 39479352, 2024). "Moreover, an animal assay confirms that downregulation of UBE2C expression further suppresses tumor growth in the context of TMZ treatment." (PMID 38634120, 2024). "Finally, we conducted a detailed examination of the variations in drug responsiveness among the cohorts characterized by high and low UBE2C+ tumour cell scores." (PMID 38894657, 2024). "Furthermore, our focus extended to examining the correlation between risk genes and OS, along with the disparities in their expression between the high UBE2C+ tumour cell score group and the low UBE2C+ tumour cell score group." (PMID 38894657, 2024).